ARMC12 (armadillo repeat containing 12)
Description:
Essential for male fertility and sperm mitochondrial sheath formation (By similarity). Required for proper mitochondrial elongation and coiling along the flagellum during the formation of the mitochondrial sheath (By similarity). Facilitates the growth and aggressiveness of neuroblastoma cells. Increases the EZH2 activity and H3K27me3 levels in a RBBP4-dependent manner, and facilitates the enrichment of polycomb repressive complex 2 and H3K27me3 on gene promoters, resulting in transcriptional repression of tumor suppressors affecting the proliferation, invasion, and metastasis of tumor cells.
Synonyms: C6orf81; FLJ25390; SPGF90
Tractability: Antibody: UniProt places it where antibodies can reach, with medium confidence.
Gene: Protein-coding gene on chromosome 6 (35,737,032 to 35,749,079, forward strand). Ensembl gene ENSG00000157343.
Subcellular location: Nucleus; Mitochondrion outer membrane
Subcellular location (Human Protein Atlas): Mitochondria
Gene Ontology:
Molecular function: protein binding
Biological process: positive regulation of cell growth; sperm mitochondrial sheath assembly; flagellated sperm motility
Cellular component: mitochondrion; nucleus; mitochondrial outer membrane
Genetic constraint (gnomAD): Loss-of-function variants: 25 observed, 39.69 expected, observed/expected ratio (o/e) 0.63, 90% interval 0.46 to 0.88. The upper end of that interval is the gene's LOEUF score, 0.88, which puts it in group 3 of 6, group 1 being the genes least tolerant of losing a copy. Missense variants: 384 observed, 446.28 expected, observed/expected ratio (o/e) 0.86, 90% interval 0.79 to 0.94. Synonymous variants: 167 observed, 185.26 expected, observed/expected ratio (o/e) 0.9, 90% interval 0.79 to 1.02.
Homologues: Orthologues: chimpanzee ARMC12 (99% identical), dog ARMC12 (88% identical), pig ARMC12 (86% identical), macaque ARMC12 (85% identical), mouse Armc12 (83% identical), rat Armc12 (83% identical), rabbit ARMC12 (82% identical), guinea pig ARMC12 (59% identical), zebrafish armc10 (21% identical), tropical clawed frog armc10 (16% identical), Caenorhabditis elegans Y67A10A.7 (14% identical). Paralogues in human: ARMCX3 (20% identical), ARMC10 (19% identical), ARMCX2 (18% identical), ARMCX1 (17% identical), GPRASP1 (17% identical), GPRASP2 (16% identical), ARMCX4 (16% identical), ARMCX6 (13% identical), GPRASP3 (12% identical), ARMCX5 (11% identical).
Diseases named in the same sentence as ARMC12 in open-access papers:
ARMC12 is named in the same sentence as 20 diseases in open-access papers, as found by Europe PMC text mining. Sharing a sentence is not in itself a finding about the gene and the disease. The quoted sentences say what the papers report.
neuroblastoma (5 papers, 2018 to 2026). Neuroblastoma (NB) is the most common solid, extracranial childhood tumor. "ARMC12 was reported to be highly expressed in clinical neuroblastoma specimens and to drive the growth and aggressiveness of neuroblastoma cell lines." (PMID 33536340, 2021). "In relation to this, ARMC12 is known to interact with nuclear protein RBBP4 to facilitate tumorigenesis of neuroblastoma." (PMID 33536340, 2021). "Here, the authors show that a new ARM protein (ARMC12) is upregulated in neuroblastoma, binds the PRC2 component RBBP4, and inhibits transcription of tumor suppressive genes." (PMID 30026490, 2018). "Armadillo repeat containing 12 (ARMC12) is located 3 kb upstream of FKBP5 and has been reported to promote neuroblastoma progression and play crucial roles in spermiogenesis." (PMID 37274192, 2023). "It has been found that blocking the interaction between ARMC12 and RBBP4 by cell‐penetrating inhibitory peptides can activate the expression of downstream genes and inhibit the tumorigenesis and invasiveness of neuroblastoma cells." (PMID 32564518, 2020). "Endogenous co-localization of ARMC12 and MYC protein was observed in ganglioneuroblastoma (GNB) or NB specimens, while their Pearson's coefficient was higher in NB tissues." (PMID 41510169, 2026).
Infertility (4 papers, 2021 to 2025). "ARMC12 is a mitochondrial peripheral membrane protein that has been implicated in the abnormal arrangement of MS, causing infertility in mice." (PMID 39516485, 2024). "To reveal the cause(s) of the infertility of the Armc12 KO male mice, we initially examined spermatozoa obtained from Armc12 KO male mice." (PMID 33536340, 2021). "The ultrastructure and formation of the mitochondrial sheath have been described in previous studies, and knockout of several genes (e.g., ARMC12, SPATA33, and VDAC3) is known to cause abnormal mitochondrial sheath formation and subsequent infertility." (PMID 38443933, 2024). "•ARMC12 interacts with GK2 (and other mitochondrial proteins, such as VDAC), which is required for mitochondrial sheath formation.•Absence of ARMC12 causes abnormal mitochondrial coiling around the flagellum, resulting in reduced motility and infertility." (PMID 41008556, 2025). "To study the infertility phenotype in more detail, we examined sperm migration into the oviduct using Armc12 KO male mice with red body green sperm (RBGS) transgenes that express enhanced green fluorescent protein in the acrosome and DsRed2 in the mitochondria." (PMID 33536340, 2021).
oligospermia (2 papers, 2017 to 2021). Decreased number of spermatozoa in the semen. "In addition, the down-regulation of the ARMC12 transcript is observed in infertile men with maturation arrest, oligospermia, and Sertoli cell-only syndrome." (PMID 33536340, 2021).
B-cell lymphoma (1 paper, 2026). "Notably, elevated ARMC12 and MYC levels were also linked to poor outcome of adrenocortical sarcinoma, B-cell lymphoma, renal clear cell carcinoma, or breast tumor." (PMID 41510169, 2026).
breast carcinoma (1 paper, 2018). "Notably, nuclear ARMC12 immunostaining was also observed in the specimens of breast cancer, colon cancer, hepatocellular carcinoma, lung cancer, pancreas cancer, prostate cancer, renal cancer, and gastric cancer, but not in their normal counterparts." (PMID 30026490, 2018).
depression (1 paper, 2020). "For depression, suggestive gene × HSV‐1 interactions was detected at ARMC12 (rs113444436, P = 1.92 × 10−6 for ADD × HSV‐1 model)." (PMID 32564518, 2020).
cancer (2 papers, 2018 to 2021). A tumor composed of atypical neoplastic, often pleomorphic cells that invade other tissues. "However, because Armc12 shows testis-enriched expression according to the Mouse ENCODE Project, the pathophysiological role of ARMC12 in this cancer is likely due to its ectopic expression." (PMID 33536340, 2021). "Low frequency of copy number alteration (amplification or deletion, 1.52%) or genetic variation (0.53%) of ARMC12 was detected in common human cancers." (PMID 30026490, 2018). "Our initial evidence also reveals the significant correlation of ARMC12 levels with the outcome of other cancer types." (PMID 30026490, 2018). "Importantly, patients with high ARMC12 levels had less survival possibility in many types of human cancers." (PMID 30026490, 2018). "In addition, gene set enrichment analysis (GSEA) of all ARMC12-correlated genes in 88 specimens revealed their close relationship with cancer metastasis." (PMID 30026490, 2018).
tumor (2 papers, 2018 to 2026). "Our previous evidences establish ARMC12 as a critical cofactor of RB binding protein 4 in enhancing polycomb repressive complex 2 activity, thus silencing tumor suppressive genes and promoting proliferation of NB cells." (PMID 41510169, 2026). "This ARMC12-MYC interplay propels tumor growth and enhances aggressiveness, underscoring the pivotal role of the ARMC12/MYC axis in driving NB progression." (PMID 41510169, 2026). "ARMC12 physically binds to RBBP4 to increase the PRC2 complex formation and EZH2 activity, leading to repressed gene expression of downstream tumor suppressive targets associated with NB progression." (PMID 30026490, 2018). "This study is helpful in extending the knowledge regarding genes crucial for tumor progression, and indicates that ARMC12 and RBBP4 are valuable as potential targets for the treatment of NB." (PMID 30026490, 2018). "MTT colorimetric studies indicated that overexpression or silencing of ARMC12 respectively facilitated and decreased the amount of viable tumor cells, than those transfected by empty vector (mock) or scramble shRNA (sh-Scb)." (PMID 30026490, 2018). "The levels of ARMC12 downstream tumor suppressive targets were obviously enhanced after intratumoral injection of RBP23." (PMID 30026490, 2018). "The mechanistic basis involves ARMC12, which functions within liquid-liquid phase-separated condensates to co-activate MYC, driving the subsequent up-regulation of NUP62, NUP93, and NUP98, elevation of NPC number, and tumor progression." (PMID 41510169, 2026). "Meanwhile, inhibitory peptide blocking the ARMC12−RBBP4 interaction is able to suppress the biological features of tumor cells, but not detrimental to normal cells lacking the endogenous ARMC12 expression." (PMID 30026490, 2018). "As a nuclear protein, ARMC12 interacts with RBBP4 protein via the ARM domain to increase the formation of PRC2 complex and facilitate the EZH2 activity, which represses the transcription of downstream tumor suppressive genes." (PMID 30026490, 2018). "Mechanistically, ARMC12 physically interacts with retinoblastoma binding protein 4 (RBBP4) to facilitate the formation and activity of polycomb repressive complex 2, resulting in transcriptional repression of tumor suppressive genes." (PMID 30026490, 2018).
ARMC12 also shares sentences with these, for which no sentence is quoted: breast tumor (1 paper); colon cancer (1); ganglioneuroblastoma (1); gastric cancer (1); hepatocellular carcinoma (1); lung carcinoma (1); male infertility (1); pancreas cancer (1); prostate carcinoma (1); renal carcinoma (1); renal clear cell carcinoma (1); Sertoli Cell-Only Syndrome (1).